LGALS3 (galectin 3)
Diseases named in the same sentence as LGALS3 in open-access papers (continued):
Sharing a sentence is not in itself a finding about the gene and the disease.
tumor (continued). "Moreover, urinary galectin-3 levels increased with tumor stage, showing that galectin-3 secretion was enhanced during tumor progression." (PMID 37189804, 2023). "In addition, LGALS3 is associated with the metabolism of HCC and lymph node metastasis, which is a key regulatory factor for tumor cell proliferation and migration." (PMID 37180150, 2023). "Of note, these tumor-specific neutrophils might act as tumor promoters by overexpressing Vegfa, Cd274, Pdcd1lg2, and Lgals3, leading to these cells being further defined as tumor-promoting neutrophils." (PMID 36650153, 2023). "Here, we were interested whether other tumor entities such as epithelial ovarian tumors (EOC) cocultured with Vγ9Vδ2 T cells release comparable amounts of galectin-3 as the cross talk of PDAC and Vγ9Vδ2 T cells did." (PMID 38259448, 2023). "The Mon Fn1 cell population is characterized by inflammatory features, including increased expression of the chemokine receptors Ccr2 and Ccr1 facilitating cell recruitment, immune suppression and tumor-promoting factors such as galectins (Lgals3/9), and the NLRP3 inflammasome inhibitor Tmem176b." (PMID 37756565, 2023). "Our data suggests that Vδ2 T cells infiltrating in tumors are inhibited in their proliferation if galectin-3 concentrations are increased since activation of Vδ2 TIL cocultured with tumor cells inhibited Vδ2 T-cell expansion and reduced effector memory activation." (PMID 38259448, 2023). "While an exact role of CD49c/CD29 interaction with galectin-3 is not described in human CD4 and CD8 αβ T cells, these interaction partners are responsible for the failure of Vδ2 T-cell proliferation in the presence of galectin-3 producing cells such as tumor cells." (PMID 38259448, 2023). "Moreover, in glioblastoma cancers, galectin-3 favors tumor invasiveness through a micropinocytosis-mediated uptake mechanism." (PMID 36873388, 2023). "Downregulation of galectin-3 could effectively inhibit tumor cell migration, invasion, cell proliferation and metastasis in osteosarcoma, thyroid, and gastric cancer (82–, 84)." (PMID 36873388, 2023). "LGALS3 plays a role in apoptosis and cell adhesion, and stimulates bone marrow mesenchymal stem cells to express interleukin-6 (IL-6) to promote tumorigenesis, inflammation of the tumor microenvironment, and metastasis." (PMID 36980828, 2023). "Besides, because of the plasma membrane proteins on the surface including galectin-3, N-cadherin, and epithelial cell adhesion molecule, tumor-derived micro-vesicles possess some unique properties such as antigenic display and homologous binding." (PMID 35477389, 2022). "The inhibition of galectin-3, along with immunotherapy, would decrease tumor growth." (PMID 36076865, 2022). "Given that galectin-3 (Gal-3) is a β-galactoside-binding lectin promoting tumor growth and metastatis, it could be a valuable target for the treatment of Gal-3-expressing neoplasms." (PMID 36432695, 2022). "Indeed, this pectin prevents glycosylated cytokines (IFNγ between others) be captured by galectin-3 and therefore allowing the chemokine gradient needed to attract lymphocytes towards the tumor." (PMID 36703969, 2022). "In addition, a heterodimeric labeled compound capable of binding to both galectin-3 and αvβ3 integrin was developed to enhance tumor specificity." (PMID 36432695, 2022). "Since both chemokines are known to regulate the recruitment and localization of anti-tumor immune cells, capturing IFN-γ by extracellular galectin-3 could provide a means of tumor immune escape." (PMID 36139125, 2022). "In addition, in tumor xenografts, unligated integrin αvβ3 interacts with galectin-3 at the plasma membrane, resulting in recruitment of KRAS and RalB." (PMID 35763345, 2022). "Moreover, galectin-3 upregulation under hypoxic and nutrient deprivation has been correlated to tumor aggressiveness and poor prognosis in several cancer type." (PMID 35682991, 2022).
tumor (continued). "Although galectin-3 impairs T-cell function, it could also increase tumor cell proliferation and migration." (PMID 35345675, 2022). "Indeed, the use of an anti-galectin-3 mAb (B2C10) promotes IFN-γ secretion by in vitro stimulated CD8+ tumor-infiltrating T lymphocytes." (PMID 36703969, 2022). "Thus, previous results suggest that galectin-3 overexpression is related to high tumor grade and poor survival and is a potential therapeutic target in human BC patients." (PMID 35334790, 2022). "For example, galectin-3 can bind to the galactose-β1,3N-acetyl-galactosamineα-Thr/Ser, an oncofetal carbohydrate antigen (Thomsen-Friedenreich antigen, TF antigen) that occurs in >90 tumour cells and can be proteolytically removed by O-glycanase." (PMID 36291660, 2022). "LGALS3 (galectin-3) is a multifunctional protein, which has a variety of biological functions, including tumor cells proliferation and differentiation, angiogenesis, tumor progression, and metastasis." (PMID 35069936, 2022). "In the last decade, galectin-3 as a target came to the forefront of anti-tumor research." (PMID 36432695, 2022). "Given human cytokines are mostly glycosylated, galectin-3 secretion could depict a general strategy for tumor immune evasion and provide a potential therapeutic target." (PMID 35053449, 2022). "However, similarly to what was discussed on galectin-1, it is unlikely that tumor-derived circulating galectin-3 reaches the concentrations required to reveal its pro-apoptotic properties in the tumor-draining lymph nodes in cancer patients." (PMID 34572756, 2021). "Indeed, galectin-3 silenced tumors elicit lymphocytes with increased degranulation capability and specific anti-tumor cytotoxicity." (PMID 34572756, 2021). "Protein analysis found higher LGALS3 levels in primary adenocarcinomas than in metastatic adenocarcinomas, and stronger LGALS3 staining in well-differentiated tumor areas compared to poorly differentiated tumor areas." (PMID 34290978, 2021). "Tumor galectin-3 specifically contains a collagen-like domain." (PMID 34290095, 2021). "In a study that examined galectin-3 (Gal-3) expression by tissue microarray constructed from 83 patients who underwent prostatectomy (83 tumor, 78 adjacent benign, and 75 benign tissues), it was shown that Gal-3 expression was significantly decreased in tumor tissue compared to benign." (PMID 35004332, 2021). "Binding of galectin-3 to activating NK cell receptor NKp30 suppresses NK cell-mediated tumor lysis." (PMID 34858978, 2021). "Taken together, effective galectin-3 inhibitors would probably need to act both intracellularly to inhibit cell-intrinsic galectin-3 as well as inactivate the abundant galectin-3 produced by stromal cells in the tumor microenvironment." (PMID 34830047, 2021). "Furthermore, ligands Galectin-3 and HLA class II were increased in monosomy 3 tumours and the expression of LAG3 correlated with the presence of an inflammatory phenotype (T cell fraction, macrophages, HLA-A and HLA-B expression: all p < 0.001)." (PMID 34503258, 2021). "Galectin-3 plays an important role in chronic inflammatory condition and is involved in the development of many diseases, including diseases of the heart, kidneys, viral infections, autoimmune diseases, neurodegenerative disorders and many neoplastic diseases." (PMID 35053194, 2021). "Considering all these arguments, tumor-derived galectin-3 may substantially impact T cell activation, expansion, and polarization of the immune responses elicited in tumor-draining lymph nodes." (PMID 34572756, 2021). "Consequently, by controlling the dendritic cell migration from the peripheral tissues (including tumors) to the draining lymph nodes, galectin-3 has a direct role in eliciting anti-tumor immune responses." (PMID 34572756, 2021). "Interestingly, in 25% (5/20) of PCNSLs, the tumor cells themselves express galectin-3, which binds to CNS glycans expressed by microglia/macrophages including MAC1, MAC3, and CD45." (PMID 34944954, 2021).
tumor (continued). "Indeed, galectin-3 interacts with proteins in the tumor extracellular matrix and colocalizes in the cell lipid nanodomains." (PMID 34572756, 2021). "Therefore, LGALS3BP and galectin-3 were proposed as new modulators of fibrosis in the tumor microenvironment." (PMID 34565385, 2021). "Similarly to galectin-3, the expression of proliferating cell nuclear antigen (PCNA) that is associated with enhanced tumor cell proliferation and invasive potential, leads to the inhibition of NK cell function via binding to activating NCR receptor NKp44." (PMID 34858978, 2021). "CHI3L1 is secreted by tumor cells and binds to galectin-3 in the TME." (PMID 35008740, 2021). "We have previously reported the synthesis and radiochemical investigation of a glycopeptide, 68Ga-NODAGA-LacN-E[c(RGDfK)]2, which may be suitable for the detection of αvβ3 integrin and galectin-3 expression in tumor endothelial and cancer cells by PET imaging." (PMID 34959383, 2021). "High galectin-3 expression was significantly associated with bigger tumor size (OR = 1.69, 95% CI = 1.01–2.84, p = 0.046) without significant heterogeneity (I2 = 48.8%, p = 0.119)." (PMID 34778306, 2021). "Galectin 3 and tumour size were found to be inversely related and correlated with OS." (PMID 34441278, 2021). "In summary, our analyses suggest that platelet GPVI binds to tumor galectin-3." (PMID 34290095, 2021). "Concerning its role, the TF antigen has been implicated in cell adhesion, as it favors the attachment of tumor cells to the endothelium through the expression of galectin-3 by endothelial cells, supporting its role in tumor invasion and therefore contributing to metastasis." (PMID 33572915, 2021). "Notably, platelet GPVI can bind to galectin-3 on tumor cells, provoking platelet-tumor cell interaction and metastasis." (PMID 34987523, 2021). "Considering the results that galecin-3 expression of ACTH producing Cushing's disease was elevated in tumor tissues of humans, there is a possibility that the galectin-3 elevation of concentric cardiomyopathy group could be related to concurrent HAC." (PMID 34722704, 2021). "In contrast, mice with xenografts derived from Galectin-3 knockdown cells exhibited a lower photo flux and tumour weight, which could be significantly restored by β-catenin overexpression." (PMID 32801345, 2020). "Although activation of MUC1-mediated signaling in an autocrine/paracrine manner caused by ligation of LGALS3 promotes uncontrolled tumor cell malignancy, no role on hormone production/secretion has been described yet for this protein." (PMID 33066652, 2020). "Galectin-3 also plays a role in immune cell migration within the tumour stroma." (PMID 33187209, 2020). "The cytoplasmic expression of galectin-3 is correlated with tumor size in SCC." (PMID 33150039, 2020). "The inhibition of the adhesion of circulating TF-positive tumor cells or micrometastasis to the endothelium via the galectin-3 pathway has been proposed as a mechanism for the antimetastatic action of TF-specific Abs, including JAA-F11 MAb, which is highly specific for alpha-anomeric TF." (PMID 32280709, 2020). "Our data suggest that the tumour expression of galectin-3 may be a predictive factor of treatment outcomes, and could be used to select patients who would benefit from mTOR inhibitor therapy." (PMID 32624579, 2020). "Consequently, this Mucin-1/galectin-3 complex is suggested to generate a shield around tumor cells, which impairs recognition by NK cells." (PMID 32063906, 2020). "Among them, LGALS3 has been reported to promote tumor development and progression in some cancers." (PMID 32528967, 2020). "In mammals including humans, results suggest that extracellular full length galectin-3 promotes transformation and metastasis of tumor cells, whilst galectin-3C can inhibit metastasis, showing that the post-translational cleavage of galectin-3 affects its function." (PMID 32033203, 2020).
tumor (continued). "The released Galectin-3 can bind to components of extracellular matrix and its membrane counterparts of other cells, which have in a wide range of biological events including cellular homeostasis, immune function, angiogenesis, tumor invasion and metastasis." (PMID 33020562, 2020). "This difference was more significant when 4T1 cells were injected in Lgals3−/− mice, where we could observe a marked decrease in the tumor growth of 4T1-shRNA-Gal-3 in comparison with 4T1-scramble cells." (PMID 31949431, 2019). "Galectin-3 (Gal-3) expressed on endothelial cells is a major actor in tumor metastasis." (PMID 31195728, 2019). "Moreover, soluble galectin-3 released from tumor cells was found to bind specifically to NKp30 thereby inhibiting NKp30-mediated cytotoxicity." (PMID 31134055, 2019). "Since elevated levels of sEng are also found in different types of cancer, it is tempting to speculate on the involvement of sEng/galectin-3 interaction in tumor progression and metastasis." (PMID 31540324, 2019). "We searched for non-carbohydrate ligands for galectin-3 that can guide a cytotoxic drug to the cancer cells by maintaining its affinity for tumor associated carbohydrate antigens." (PMID 31842510, 2019). "LGALS3 was also found to promote GBM and was associated with tumor risk and prognosis." (PMID 32047515, 2019). "Therein as an important regulator of the Wnt/β-catenin signaling pathway, galectin-3 could activate the epithelial–mesenchymal transition (EMT) in tumor cells to promote the invasion and metastasis of cancer." (PMID 30410421, 2018). "Moreover, interactions between MUC4 glycans and galectin-3 were shown to also mediate docking of circulating tumor cells to the surface of endothelial cells." (PMID 30236127, 2018). "Moreover, a gene expression profile performed on galectin-3 transfectants revealed activation of genes involved in tumor growth and progression, among which were PCNA (proliferating cell nuclear antigen), replication factor C and Rb retinoblastoma gene." (PMID 29393868, 2018). "Recent studies shows that Galectin-3 secreted by tumor cells binds TF-antigen on MUC1." (PMID 29507546, 2018). "Of the proteomic data, the most significant change shared in common by the three invasive MM concerned galectin-3, a multifunctional protein distributed both intracellularly and in the tumor stroma, which is involved in the development, progression, invasion and metastasis of many cancers." (PMID 29662647, 2018). "Inhibition of galectin-3 in human tumor biopsies enhanced IFN-γ-induced CXCL-9 chemokine expression, suggesting that the blockade of galectin-3 in tumor cells may promote T cell tumor infiltration and activation." (PMID 29389859, 2018). "Extracellular galectin 3 secreted by tumour cells has also been shown to induce angiogenesis." (PMID 29666124, 2018). "The tumor cells produce the extracellular galectin-3 (a lectin that binds to glycans of glycoproteins in ECM), which binds to the glycoprotein IFN-γ and prevents it from inducing secretion of above chemokines, thus impedes the cytotoxic T-cell recruitment in the TME77." (PMID 29983921, 2018). "Galectin-3 (Gal-3) is a promising target in cancer therapy with a high therapeutic potential due to its abundant localization within the tumor tissue and its involvement in tumor development and proliferation." (PMID 30236114, 2018). "Thus, COX-2, podoplanin and galectin 3 are obviously intertwined in their support to tumor growth in different fashions and highlight COX-2 as valuable target in lymphangiogenesis." (PMID 30305116, 2018). "Galectin-3 as a β-galactoside-binding protein, has been found to be involved in tumor cell growth, anti-apoptosis, adhesion, angiogenesis, invasion, and distant metastases, indicating that it may play a pivotal role in cancer development and progression." (PMID 30410421, 2018).
tumor (continued). "Extracellular galectin 3 may influence tumour progression by impeding the endocytosis of key receptors, including TGFβ and EGF, while at the same time inducing endocytosis of β1 integrins." (PMID 29666124, 2018). "Furthermore, we see a statistically significant upregulation in members of the galectin family – galectin 3 and galectin 1 – a group of proteins that bind β-galactoside and whose expression correlates with tumour development and invasiveness." (PMID 29666124, 2018). "Galectin-3 (Gal-3) is a β-galactoside-binding protein with multiple functions including regulation of inflammation, cell growth, signaling, chemotaxis, cell-matrix interactions, tumor progression, and metastasis." (PMID 29164071, 2017). "Galectin-3, in particular, plays an important role in tumor progression." (PMID 28952509, 2017). "We reason that extracellular galectin-3, secreted by the tumor, may accumulate in the tumor microenvironment by binding to the highly glycosylated ECM." (PMID 28986561, 2017). "Galectin-3 was suggested to be expressed by tumor cells in 84% of samples, and it might have dual functions: weak expression correlated with increased tumor invasion and growth, while positive expression with decreased invasion and growth." (PMID 28355349, 2017). "Galectin-3 has been shown to modulate fibronectin tumor cell motility." (PMID 29185464, 2017). "Altogether, knocking down Galectin-3 slightly decreased tumor cell proliferation of B-cpap cells." (PMID 29254179, 2017). "In mice bearing human tumors, galectin-3 reduces IFNγ diffusion through the tumor matrix." (PMID 28986561, 2017). "Glycoprotein/galectin-3 lattices could therefore retain glycosylated soluble factors, such as cytokines and in particular IFNγ, limiting their diffusion inside the tumor." (PMID 28986561, 2017). "We postulate that CEA in excess of 1ng/ml may result in intercellular binding of CEA to galectin-3 on tumor cells, thereby inhibiting cell migration." (PMID 28977916, 2017). "Hence, galectin-3 retains IFNγ in the tumor microenvironment, thereby decreasing the extension of a CXCL9 gradient." (PMID 28986561, 2017). "We examined whether galectin-3 was able to modulate IFNγ-induced CXCL9 expression in human tumor cells." (PMID 28986561, 2017). "However, 15 and 20 days p.o.i we observed an increased tumor volume in Lgals3−/− mice in comparison with Lgals3+/+ (P < 0.01)." (PMID 27526676, 2016). "Galectin-3 plays an important role in processes that fuel the tumor growth and metastasis." (PMID 27526676, 2016). "Expression of galectin-3 also promotes cell aggregation to allow tumor cells to avoid anoikis." (PMID 27483328, 2016). "Together, these data suggest that increased expression of cellular galectin-3 and elevated concentration of galectin-3 in circulating system may contribute to tumor progression and metastasis." (PMID 27191983, 2016). "In addition to angiogenesis, galectin-3 has also been shown to participate in other process required to constitute the tumor vasculature, a process named vasculogenic mimicry." (PMID 27242966, 2016). "Galectin-3 induces tumor cell, endothelial cell, and leukocyte migration, favoring either the exit of tumor cells from a stressed microenvironment or the entry of endothelial cells and leukocytes, such as monocytes/macrophages into the tumor organoid." (PMID 27242966, 2016). "It is possible that, like galectin-3, the increased interactions of these galectin members with cancer-associated TF/MUC1/4 in circulation may also influence tumor cell metastatic spread." (PMID 27066458, 2016). "Galectin-3 also regulates tumor cell migration through other mechanisms." (PMID 27242966, 2016). "Therefore, through regulation of endocytosis and intracellular trafficking of glycoproteins like integrins, galectin-3 assumes a novel role in the control of tumor cell adhesion and migration." (PMID 27242966, 2016).